INS (insulin)
Diseases named in the same sentence as INS in open-access papers (continued):
Sharing a sentence is not in itself a finding about the gene and the disease.
diabetes (continued). "Thirdly, data on fasting insulin levels and glycosylated hemoglobin are not available in the database, so it is impossible to compare the accuracy of predicting diabetes risk between TyG and HOMA-IR or glycosylated hemoglobin." (PMID 33161902, 2020). "Both attention and working memory are involved in setting goals and decision making, which in the context of obesity and diabetes can include decisions on what to eat, when and how much to exercise, when and how much to sleep, and self-monitoring diet, physical activity and insulin." (PMID 33117225, 2020). "Thus, for diabetes, the main compounds used in monotherapy are the biguanides (26.92%), insulin therapy (20.0%) and sulfonylureas (10.0%)." (PMID 32634013, 2020). "The impaired spatial arrangement and connections between cells creating islets of Langerhans as well as altered expression of G protein-coupled receptors (GPCRs) often lead to dysfunction of insulin-secreting pancreatic β cells and can significantly contribute to the development of diabetes." (PMID 32917053, 2020). "The Centers for Disease Control and Prevention Guideline recommends lowering perioperative blood glucose levels, although there have been few studies in which the effect of preoperative insulin therapy in patients with diabetes, especially in those with chronic hyperglycemia, was investigated." (PMID 32993618, 2020). "We hypothesize that shortly after surgery an elevated parasympathetic outflow and reduced cortisol axis activity may improve insulin sensitivity and act together with the increased incretin hormones to promote diabetes remission." (PMID 31983031, 2020). "Most hypoglycemic agents used for diabetes treatment, including synthetic insulin and western medicine, may bring about side effects, such as hypoglycemia and myocardial infarction." (PMID 31790971, 2020). "Additionally, if needed, the Swedish patients with dementia and diabetes are provided with nursing assistance regarding insulin injections, therefore the possibility of inappropriate care due to cognitive decline should be decreased." (PMID 32741836, 2020). "Moreover, one of the common drugs used in diabetes (peroxisome proliferator-activated receptors [PPAR]-γ agonists) increases metabolic efficiency by enhancing insulin sensitivity to reduce Aβ levels." (PMID 33250703, 2020). "IR can be identified earlier than insulin secretion failure and is not always associated with the development of diabetes when islet cell secretion can keep up with normal insulin demand." (PMID 33381523, 2020). "It has been proposed that impairment in insulin secretion, in utero undernutrition and epigenetic alterations to the genome might contribute to the pathogenesis of diabetes in the low BMI group." (PMID 33183277, 2020). "However, subcutaneous insulin therapy has proved to be a burden on the lifestyle of people with diabetes." (PMID 32785196, 2020). "While diabetes does not cause pain directly, its treatments and complications, such as injections of insulin, infections, and wounds and cuts that are slow to heal, healing, can cause pain." (PMID 32908934, 2020). "Hypogonadism due to therapy with GnRH agonists in men with prostate cancer is associated with increased fat mass, whereas testosterone treatment in hypogonadism results in improved insulin sensitivity and decreased fat mass in patients with type 2 diabetes mellitus." (PMID 32535783, 2020). "Additionally, the upregulated DEGs in the diabetes-DFE-VS-diabetes comparison were mainly enriched in the metabolic and insulin signaling pathways." (PMID 31790971, 2020). "However, further studies of the importance of insulin clearance in pathogenesis of diabetes remain to be done." (PMID 33658981, 2020). "Diabetes, mostly non-insulin dependent, was present in 44% of subjects." (PMID 32270960, 2020). "Of note, DCI may improve the insulin sensitivity of α-cells, which could control glucagon levels in patients with diabetes mellitus." (PMID 33153126, 2020).
diabetes (continued). "Over time, diabetes induces critical alterations in the skin, including a dysfunctional ability for skin regeneration after a wound, which can be partially attributed to insulin resistance." (PMID 33023156, 2020). "Diabetes mellitus (DM) is a chronic complex metabolic disorder that occurs in response to complete or insufficient cessation of insulin secretion or synthesis and/or insulin peripheral resistance causing disturbances in carbohydrate, proteins, and fat metabolism." (PMID 33061252, 2020). "The present study demonstrated that vitamin D and omega-3 co-supplementation for 8 weeks in women of reproductive age with pre-diabetes and hypovitaminosis have positive effects on fasting blood insulin, glucose and HDL-C levels, HOMA-B, waist circumference and weight." (PMID 32435279, 2020). "However, once glucose impacts NKA activity too, the described limiting insulin effect should be evaluated also in the presence of variable and elevated glucose levels, as in diabetes states." (PMID 32377524, 2020). "It is possible that after the diagnosis of diabetes in 24–28 pregnancy week (based on the guidelines) weight gain is limited as a result of implementing typical recommendations for changing diet, physical activity, or treatment with insulin." (PMID 32599847, 2020). "A high-salt diet may increase fasting ghrelin levels, thus, regulate appetite, glucose homeostatic, insulin resistance and fat accumulation, which most likely involves in the mechanism of obesity and diabetes." (PMID 31996216, 2020). "ZnO NPs effectively reverse diabetes-induced pancreatic structural, ultrastructural, and functional injuries; normalize blood glucose and serum insulin levels; and restore the sensitivity of the insulin receptor to insulin." (PMID 32069903, 2020). "Diabetes mellitus is a chronic disease that includes several physiological dysfunctions with different etiologies: it is characterized by chronic hyperglycemia due to either a defect in insulin secretion and/or functionality." (PMID 33467298, 2020). "The cat had concurrent diabetes mellitus, which responded to insulin therapy and diet." (PMID 32110427, 2020). "Moreover, a reduced insulin secretion in permanent neonatal diabetes patients affects glucose metabolism and severe hypertension is observed in Liddle’s syndrome patients." (PMID 32759790, 2020). "Ketone bodies and acetate levels are increased in diabetes due to increased fatty acid oxidation and ketogenesis caused by lack of insulin or insulin resistance." (PMID 33304273, 2020). "In addition, the well-known specific eMNs of diabetes, insulin related BPs (GO:0032868_response to insulin, GO:0032869_cellular response to insulin stimulus) are also in the list." (PMID 33381155, 2020). "It is possible that this represents a compensatory mechanism in diabetes, which may be mediated e.g. via miRNAs involved in insulin signalling and glucose transport via the PI3K/Akt/m-TOR signalling pathway." (PMID 33303872, 2020). "The deficiency in basic knowledge on insulin pumps among healthcare providers could lead to potential mishandling of insulin pumps among patients with diabetes." (PMID 33334003, 2020). "In the United States, approximately 400,000 patients with diabetes use insulin pumps." (PMID 33334003, 2020). "Our data provide evidence that DCI could be useful to improve the insulin sensitivity of pancreatic α-cells in diabetes treatment." (PMID 33020399, 2020). "Few PCPs knew that patients with diabetes travelling to the east region may need to increase their insulin dose, while those travelling to the west region may need to decrease their insulin dose (6.8 and 6.2%, respectively)." (PMID 32972370, 2020). "Moreover, miR-192 was upregulated in type 1 diabetes mellitus, regulated pancreatic β cell development, and inhibited insulin secretion through suppressing GLP-1 expression." (PMID 32013999, 2020). "Changes in glucose and insulin in the diabetes model lead to oxidative stress." (PMID 32312941, 2020).
diabetes (continued). "Patients with diabetes should achieve good control of their blood glucose by following a nutritious meal plan and exercise program, losing excess weight, implementing necessary self-care behaviors, and taking oral medications or insulin therapy." (PMID 32610588, 2020). "We provided multiple pieces of evidence for the first time that the highly expressed TJ molecule Cldn4 may be involved in regulating the FS of the pancreatic insulin‐secreting β cells with implications in translational research for better diabetes therapies." (PMID 31562747, 2020). "Raised apelin levels were found in both insulin-resistant mice and type 2 diabetes mellitus patients (Xu, Tsao & Yue, 2011), which supported the speculation that insulin can stimulate APLN secretion." (PMID 33240613, 2020). "While secretion of insulin is known to be compromised in diabetes, we have been interested in exploring whether the diabetogenic process might entail detectable mechanistic changes in how insulin granules fuse during exocytosis." (PMID 33164744, 2020). "Type 2 diabetes mellitus is characterised by impaired glucose homeostasis resulting from insulin resistance in peripheral tissues, such as liver and skeletal muscle, as well as from relative impairments in insulin release by pancreatic β-cells." (PMID 32472192, 2020). "Age, body weight, gender, insulin usage, nutritional therapy, body mass index (BMI), the presence of diabetes complications, intensive care unit admission, and infection were reported as possible risk factors that may increase the risk of hypoglycemia." (PMID 32133264, 2020). "A dysregulation of the insulin signaling with reduced downstream pathways represents a common pathophysiological aspect in the development of both peripheral and central alterations leading to diabetes/obesity and AD." (PMID 32733190, 2020). "A DRP was assigned to the category diabetes-related if an antidiabetic drug (oral and injectable antidiabetics including insulin) was involved, for example a drug-drug interaction between an antidiabetic drug and an antihypertensive drug was categorized as diabetes-related." (PMID 32903568, 2020). "Insulin treatment partly reversed these alterations by diabetes." (PMID 32290519, 2020). "But too much, particularly spread through the day rather than eaten in just one or two sessions, can lead to tooth decay and can increase the amount of insulin you release, leading, over a lifetime, to a greater chance of weight gain (insulin encourages fat deposition) and diabetes." (PMID 31951616, 2020). "In line, in this study we observed these metabolites to be associated with insulin sensitivity in individuals without diabetes mellitus, as well as in individuals with diabetes mellitus." (PMID 32124065, 2020). "However, the amount of insulin excreted in urine varies physiologically (e.g., fasting and post-prandial) and in pathological conditions (obesity, diabetes) depending on the affected nephron region (e.g., glomerulopathy vs. tubulopathy)." (PMID 32850773, 2020). "Levels of GLUT1 protein are unaffected by diabetes or insulin treatment." (PMID 32591906, 2020). "Patients are supported with more flexible and scholarly access to skills and knowledge for various aspects of diabetes self-management, including diabetes prevention, lifestyle and dietary guidance, exercise, insulin injection, and complications monitoring, to list a few." (PMID 32548087, 2020). "Physical activity improves lipid metabolism and blood pressure, it may also reduce total daily insulin requirements in people on insulin treatment and is at least as effective in diabetes prophylaxis as medicines." (PMID 33322719, 2020). "Previous studies indicated that BMI was positively correlated with insulin secretion in individuals with diabetes, which might reflect compensatory augmentation of insulin secretion against insulin resistance." (PMID 32821293, 2020).
diabetes (continued). "Moreover, a recent study conducted only in T2D insulin-treated patients demonstrated that the education of family members in diabetes self-glucose monitoring reduces the diabetes distress and improves autonomy and self-confidence." (PMID 33153229, 2020). "A better understanding of the importance of skeletal muscle ECM remodeling, integrin signaling, and other factors that regulate insulin activity may help in the development of novel therapeutics for managing diabetes and other metabolic disorders." (PMID 32481704, 2020). "The other studies did not report any correlation, but since insulin use is generally associated with advanced diabetes, one would presume a positive correlation anyway." (PMID 33437546, 2020). "Diabetes mellitus comprises a group of metabolic disorders characterized by a relative lack and/or reduced response to endogenous insulin on target cells, leading to metabolic and vascular complications related to hyperglycemia that affect several organs and systems." (PMID 33312173, 2020). "These flavonoids regulated biomarkers of glycemic control, lipid profiles, renal function, hepatic enzymes, and antioxidant enzymes, and modulated signaling pathways related to glucose uptake and insulin sensitivity that are involved in the pathogenesis of diabetes and its related complications." (PMID 32977511, 2020). "However, as insulin acts as a trophic factor on the exocrine pancreas, the pancreatic mass shrinks with the natural course of diabetes." (PMID 31929591, 2020). "Furthermore, increasing the oleic acid intake improved insulin sensitivity and elicited beneficial effects on both obesity and type 2 diabetes mellitus." (PMID 32824501, 2020). "Given that there is likely to be a close association between mitochondrial morphology and function, altered mitochondrial dynamics may well contribute to defective insulin secretion in diabetes." (PMID 32894309, 2020). "Previously, we have shown that young, lean insulin-resistant offspring of parents with type 2 diabetes and individuals with diabetes have a 25–48% lower mitochondrial oxidative capacity and fat oxidative capacity compared with healthy control participants, which was associated with increased IMCL." (PMID 32185462, 2020). "The first clinical trial tested whether intervention with insulin can delay the appearance of overt diabetes was the Diabetes Prevention Trial–Type 1 (DPT-1)." (PMID 32872668, 2020). "Adiponectin may mediate the beneficial effects of PPARγ agonists for the treatment of diabetes, as it is an insulin-sensitizing adipokine that affects hepatic glucose output and decreases triglyceride content in the liver and muscle." (PMID 31918918, 2020). "Although high levels of ketones often reflect a deficiency in insulin secretion in diabetic patients, no subjects in this study had diabetes or impaired glucose metabolism." (PMID 32375859, 2020). "Even in individuals without diabetes mellitus, insulin resistance and fasting insulin levels are associated with asymptomatic atherosclerosis and coronary artery disease." (PMID 32514025, 2020). "For example, 10–15% of people initially diagnosed with type 2 diabetes are found to have evidence of beta-cell autoimmunity in the form of circulating islet autoantibodies and often progress to an insulin-requiring form of diabetes termed latent autoimmune diabetes in adults (LADA)." (PMID 32314012, 2020). "We identified an intragenic CpG site in the gene encoding chromatin target of PRMT1 (CHTOP) that exhibits complementary tissue specificity to INS and may be used to increase confidence of detecting islet damage in youth with prediabetes and diabetes." (PMID 32736653, 2020). "The trend analysis of the key diabetes parameters, blood glucose, insulin, and carbohydrate, during acute infection suggests that there is a dramatic shift in the evolution of blood glucose, insulin, and carbohydrate (for detailed information, see Multimedia Appendices 1 and 3)." (PMID 32784178, 2020).
diabetes (continued). "The MAGNA VICTORIA study was a single-centre, parallel-group trial in 50 individuals with type 2 diabetes mellitus (BMI >25 kg/m2) who were randomly assigned (1:1, stratified for sex and insulin use) to receive liraglutide 1.8 mg once daily or placebo for 26 weeks, added to standard care." (PMID 31690988, 2020). "Elderly patients with diabetes exhibit a combination of impaired insulin secretion and increased insulin resistance, which might be due to a combination of adiposity and sarcopenia." (PMID 32640726, 2020). "Treatment that can improve the insulin sensitivity of α-cells could control glucagon levels in patients with diabetes mellitus." (PMID 33020399, 2020). "In early diabetes, an increase in insulin may drive and sustain inflammation in macrophages and thereby contribute to the chronic low-grade inflammation." (PMID 33182622, 2020). "Few participants knew that patients with diabetes travelling to the east region may need to increase their insulin dose, while those travelling to the west region may need to decrease their insulin dose." (PMID 32972370, 2020). "In sum, convergent evidence has illustrated that obesity or diabetes triggers neuroinflammation, insulin resistance, the mitochondrial perturbation in the brain, which could impair hippocampus neuroplasticity and hence cognitive function." (PMID 33379163, 2020). "Our results support the hypothesis that oral magnesium-rich BDSW supplementation improves insulin-sensitivity metrics in prediabetes and could be used to establish a public health strategy to reduce the incidence of diabetes." (PMID 32085495, 2020). "To evaluate the effects of T1D on this fungal infection and the modulatory effects of insulin, we induced diabetes in C57Bl/6 male mice (alloxan, 60 mg/kg), infected the mice (Pb18, 1 x 106 cells), and treated the mice with neutral protamine Hagedorn (NPH) insulin (2 IU/600 mg/dL blood glucose)." (PMID 33312173, 2020). "However, insulin use, diabetes oral medication, and hypertension medication were higher among people who have low serum magnesium." (PMID 32351381, 2020). "However, insulin treatment for diabetes was significantly more predominant in the preoperative as compared to the intraoperative group." (PMID 32523777, 2020). "Notably, the expression of ErbB3 itself increases during fasting and diabetes, a phenomenon that can be reversed by insulin administration, indicating that ErbB3 expression is under direct regulation of hormonal or nutrient status." (PMID 32372975, 2020). "In this study, we aimed to evaluate the influence of insulin production on immune system after the onset of diabetes, and we showed that the duration of honeymoon period could be related to the onset of other autoimmune conditions." (PMID 32215008, 2020). "Half (53%) had pre-diabetes and 92% a reduction in insulin sensitivity." (PMID 33208826, 2020). "From the clinical point of view, the presence of retinopathy and nephropathy is certainly not the cause of polyneuropathy, they are all a consequence of metabolic disorders in diabetes mellitus or, more correctly, insulin resistance: one of the main elements of the development of diabetes mellitus." (PMID 32831065, 2020). "We believe that DU plus conventional insulin therapy might be the ideal treatment method for insulin therapy for non‐ICU hospitalized patients with diabetes." (PMID 31168938, 2020). "Given that much of the published and ongoing work on hypusine biosynthesis in mice has studied eIF5AHyp in the context of diabetes, we had hypothesized that eIF5AHyp expression would be identified predominantly in the insulin-producing beta cell population." (PMID 32208453, 2020). "Additionally, apelin-13 treatment ameliorated diabetes-induced reduction in islet mass and insulin content in Akita mouse which is a mouse model for ER stress-induced diabetes." (PMID 32517197, 2020).